APLN (apelin)
Diseases named in the same sentence as APLN in open-access papers (continued):
Sharing a sentence is not in itself a finding about the gene and the disease.
ischemia (25 papers, 2013 to 2026). A hypoperfusion of the BLOOD through an organ or tissue caused by a PATHOLOGIC CONSTRICTION or obstruction of its BLOOD VESSELS, or an absence of BLOOD CIRCULATION. "Previous studies have shown that apelin-13 plays an important role in cerebral ischemia and ischemic stroke, and changes in the expression level of endogenous apelin-13 following ischemia has diagnostic and therapeutic relevance." (PMID 36034795, 2022). "These different studies put forward the ability of apelin-13 to reduce damages of ischemia with reduction of oxidative stress and promotion of angiogenesis resulting in protective effects on tissues." (PMID 36973482, 2023). "The heart was perfused a solution with Pyr1-apelin-13 (10 nmol/L) prior to ischemia or after ischemia." (PMID 36986889, 2023). "To support the blood flow reperfusion data, we evaluated the ability of Pyr-apelin-13 to promote collateral vessel formation following ischemia by measuring vascular density on cross-sections of the ischemic adductor and calf muscle of all groups of mice." (PMID 37636297, 2023). "Endogenous apelin has been shown to participate in the collateral vessel formation processes during ischemia." (PMID 37636297, 2023). "A disturbance of apelin expression disrupts the recovery of contractile function of the isolated mouse heart after ischemia (30 min) and reperfusion (40 min)." (PMID 36986889, 2023). "Oxygen and glucose deprivation are the main consequences of ischemia, which are related to the abnormal expression of the apelin/APJ system." (PMID 32194492, 2020). "In order to discover a biomarker that triggers the diabetic myocardial ischemia reperfusion injury, the cardiovascular disease-related protein, Apelin, was examined in both myocardial tissues and serum." (PMID 33342766, 2020). "Meanwhile, the ischemia reperfusion injury size and heart weight index were significantly decreased under Apelin treatment." (PMID 33342766, 2020). "Likely by acting on this signaling pathway, Apelin reduced infarct size and improved the impaired cardiac function induced by ischemia." (PMID 29245958, 2017). "First, apelin reduces ischemia/reperfusion injury-induced oxidative stress by increasing the activity of antioxidant enzymes in kidneys, such as superoxide dismutase (SOD), catalase (CAT) and glutathione peroxidase (GSH-Px)." (PMID 28167898, 2017). "Most recently, apelin-13 was also demonstrated to protect brain from ischemia/reperfusion (IR) injury through activation of AKT and ERK1/2 signaling pathways in a mouse focal transient cerebral ischemia model." (PMID 26391329, 2015). "Previously, it has been demonstrated that Apelin-13 is able to inhibit acute ischemia-induced myocardiocyte apoptosis by activating the PI3K/Akt singaling pathway." (PMID 23403698, 2013). "The lack of protective effects of apelin-13 is in agreement with our findings, suggesting that the apelin/APLNR signaling pathway may be either disrupted or insufficient to counteract the deleterious effects of ischemia-induced AKI." (PMID 40177358, 2025). "The results suggest that apelin-13 could interfere with cellular regeneration after ischemia-induced AKI, switching the adaptive repair mechanism to maladaptive response by downregulating tubular mitosis." (PMID 40177358, 2025). "At the same time, studies in which apelin was administered before cardiac ischemia are also of practical importance, since in cardiac surgery using cardioplegic arrest the heart is subjected to ischemia." (PMID 36986889, 2023). "Our [68Ga]Ga-AP747 PET results showed that APJ was overexpressed longer than a week after ischemia, suggesting that a prolonged apelin-13 supplementation could be advantageous for post-ischemic hindlimb perfusion recovery." (PMID 36973482, 2023). "The overexpression of apelin can stabilize the lymphatic vasculature under ischemic injury, indicating that apelin has a role in maintaining lymphatic vessel integrity and cardiac function after the onset of ischemia." (PMID 38178871, 2023).
ischemia (continued). "Apelin-12 had a more pronounced inotropic effect if it was infused prior to ischemia." (PMID 36986889, 2023). "In CKD, apelin attenuates renal fibrosis and alleviates renal ischemia/reperfusion injury." (PMID 34206927, 2021). "Taken together, these data suggested that increased number of APJ+ stem cell at ischemia area via upregulation of SDF-1α/CXCR-4 pathway maybe responsible for apelin-BMCs therapy-mediated cardiac repair." (PMID 24039710, 2013). "Our study demonstrated for the first time that apelin treatment enhanced endothelial cell function under hypoxia and high glucose exposure as well as improved blood flow reperfusion and functional recovery of the hindlimb following ischemia in a diabetic condition." (PMID 37636297, 2023). "Moreover, overexpression of APLN reduced the leakiness of vessels in models of ischemia." (PMID 32545380, 2020). "We found that APLNR was induced in the renal tubular cells of the ischemia-induced AKI model, whereas initial/prior apelin-13 administration affected tubular proliferation after renal I/R." (PMID 40177358, 2025). "Apelin-12 and its analogues (AI or AII) were added to cardioplegic solution before ischemia or after ischemia at the final concentrations of 70, 140, and 280 μmol/L." (PMID 36986889, 2023). "Since VEGF-A did not provide a gain of perfusion in the ischemic hindlimb, we investigated the potential of apelin (APLN), a vascular growth factor inducing capillary sprouting and maturation, to improve perfusion after ischemia induction." (PMID 23613948, 2013). "Apelin treatment improves revascularization in nondiabetic models of ischemia, however, its role on angiogenesis in diabetic conditions remains poorly investigated." (PMID 37636297, 2023). "Notably, compared with the MSC group, MSC survival was significantly increased in the Apelin-13-MSC group, indicating that Apelin-13 pretreatment improved the tolerance capacity of MSCs in the presence of ischemia." (PMID 35355588, 2022). "Moreover, the expressions of apelin and APJ in neurons in the early stage of ischemia are induced by increased SP1, which is possibly mediated by HIF-1α." (PMID 32194492, 2020). "The expression of apelin and APLNR is only increased early after ischemia in heart." (PMID 28167898, 2017). "Pretreatment with apelin-13 before ischemia did not reduce infarct size." (PMID 36986889, 2023). "Furthermore, other studies reported apelin/APJ upregulated expression under hypoxic and normoglycemic conditions in cultured vascular cells and peripheral mononuclear cells, as well as in mouse lungs following ischemia." (PMID 37636297, 2023).
glioblastoma (24 papers, 2014 to 2025). The most malignant astrocytic tumor (WHO grade IV). "In contrast to this study in glioblastoma, we find a consistent benefit of depleting Apelin in epithelial breast and lung cancer, associated with normalized vessel function, decreased hypoxia, and consequently reduced metastases." (PMID 31267692, 2019). "In glioblastoma cells, upregulation of both the APLN and the Apelin receptor (APLNR) allow control over the invasiveness of tumor cells take place." (PMID 38804848, 2024). "Knocking out APJ in glioblastoma cells reduced tumor growth and angiogenesis, suggesting that targeting the apelin/APJ system is a promising strategy for preventing angiogenesis in glioblastoma." (PMID 36034795, 2022). "On the other hand, Mastrella and colleagues recently reported that reduced apelin expression led to accelerated glioblastoma cell invasion." (PMID 34234274, 2021). "The results of these studies undercover the potential of apelin/APJ signaling as a drug target for glioblastoma." (PMID 33912466, 2021). "We also showed that anti-VEGF therapy resulted in decreased APLN expression in the glioblastoma-stem-like model, resulting in increased tumor cell invasiveness." (PMID 32545380, 2020). "In the brain aplnr is present at low levels in normal human meningeal blood vessels, and both apln and ir-apelin, and aplnr expression have been found in microvascular proliferations in human glioblastoma specimens." (PMID 32315363, 2020). "The combination of anti‐angiogenic treatment with Apelin‐F13A seems to be promising in glioblastoma, but due to its unclear mechanism of action its wider applicability as potential therapeutic in other types of cancers remains questionable." (PMID 31267692, 2019). "Apelin expression is elevated in a number of cancers, such as lung non-small cell carcinomas, gastroesophageal, glioblastoma, colon, hepatocellular, prostate, endometrial, and oral squamous cell carcinoma." (PMID 31492821, 2019). "They demonstrated that glioblastoma stem-like cells expressing higher apelin levels were better able to initiate tumor development." (PMID 31492821, 2019). "A recent publication found that Apelin depletion presents a double‐edged sword in glioblastoma, since it enhanced tumor cell invasion, while at the same time reducing vascular density, without accompanied changes in immune cell infiltration." (PMID 31267692, 2019). "Collectively, these in vivo data provide a strong basis for the clinical potential of apelin/APLNR signalling as a therapeutic target in glioblastoma." (PMID 29053791, 2017). "We report the identification of the vasoactive peptide apelin as a central regulator for endothelial-mediated maintenance of glioblastoma patient-derived cells with stem-like properties." (PMID 29053791, 2017). "Given the concerns about the current therapeutic regime and the intrinsic resistance to TMZ, targeting apelin signalling presents a new opportunity for use in the treatment of glioblastoma." (PMID 29053791, 2017). "Pharmacological blockade of apelin hampers glioblastoma cell expansion and improves survival in xenografted mice." (PMID 29053791, 2017). "Here, we used a mass spectrometry proteomic analysis of the endothelial cell secretome and identified the vasoactive peptide apelin as a central regulator of the expansion of glioblastoma patient-derived cells with stem-like properties." (PMID 29053791, 2017). "Genetic and pharmacological targeting of apelin cognate receptor abrogates apelin- and endothelial-mediated expansion of glioblastoma patient-derived cells with stem-like properties in vitro and suppresses tumour growth in vivo." (PMID 29053791, 2017). "In MG3, genes involved in endothelial regulation (ESM1, APLN, ALCAM) and ligands for αVβ3 integrin (EDIL3 and POSTN) were expressed at higher levels compared to MG1 and MG5, the latter of which recruit tumour-associated macrophages (TAM) in adult glioblastoma." (PMID 37679810, 2023).
glioblastoma (continued). "Interestingly, in glioblastoma, a representative tumor that shows VM, a reduction in apelin expression led to accelerated glioblastoma cell invasion." (PMID 36776217, 2023). "Apelin is secreted from the endothelial cell near Glioblastoma stem-like cells (GSCs)." (PMID 36421846, 2022). "Additional research has been done to elucidate the system’s potential role in neurogenesis, the pathophysiology of Glioblastoma multiforme, and the protective effects of apelin peptides on some neurological and psychiatric disorders-ischemic stroke, epilepsy, Parkinson’s, and Alzheimer’s disease." (PMID 36421846, 2022). "Knockdown of APLN resulted in reduction of tumor vasculature in glioblastoma." (PMID 33912466, 2021). "Importantly, in this glioblastoma study, it was also reported that a combination of Apelin‐F13A with anti‐VEGFR2 therapy is superior to either intervention alone." (PMID 31267692, 2019). "As such, targeting apelin may represent an effective novel therapeutic approach to treat glioblastoma." (PMID 29053791, 2017). "Furthermore, high levels of vascularization in human glioblastoma are correlated with high expression levels of Apelin and APJ." (PMID 27828952, 2016). "However, apelin expression reduction was found to promote glioblastoma cell invasion." (PMID 33912466, 2021). "Therefore, the apelin/apelin receptor signalling nexus may operate as a paracrine signal that sustains tumour cell expansion and progression, suggesting that apelin is a druggable factor in glioblastoma." (PMID 29053791, 2017). "Apelin (APLN), an endogenous ligand of the APJ receptor, is aberrantly overexpressed in diverse malignancies, including glioblastoma, esophageal cancer, hepatocellular carcinoma, and prostate cancer." (PMID 41145436, 2025). "The apelin/APJ system is closely related to the occurrence and development of tumors, such as cholangiocarcinoma, osteosarcoma, glioblastoma, and renal cell carcinoma." (PMID 40165344, 2025). "The results demonstrated that APLN and APLNR mRNA expression were significantly increased in CNS cancers, including both low-grade glioma (LGG) and glioblastoma (GBM), when compared with normal CNS tissues." (PMID 36193059, 2022). "The neurovascular peptide Apelin and its receptor APLNR are upregulated during glioblastoma pathology." (PMID 34359800, 2021). "Overexpression of APLN and its receptor APJ is further detected in highly proliferating micro-vessels in primary glioblastoma tissues when compared to normal brain tissues, providing further evidence for the vital role of APLN during tumour angiogenesis." (PMID 28487489, 2017). "Dichotomous roles of apelin/APJ signaling in tumor invasion and angiogenesis in glioblastoma." (PMID 33912466, 2021). "Besides, the authors also discovered that apelin-F13A could bind to APJ, leading to the inhibition of glioblastoma cell invasion and tumor angiogenesis." (PMID 33912466, 2021). "Analysis of all three databases revealed a significant increase in APLN mRNA in glioblastoma tissue, as compared to non-tumour samples, which might be due to endothelial abundance in these grade IV tumours." (PMID 29053791, 2017). "However, APLN staining did not coincide with NESTIN-positive tumour cells, but rather with vascular tracks, supporting endothelial cells as a potential source for apelin in glioblastoma, consistent with a recent report in colorectal cancer-derived endothelial cells." (PMID 29053791, 2017).
coronary artery disease (22 papers, 2012 to 2025). "Likewise, another study on the Turkish population reported that patients with coronary artery disease seem to have lower apelin levels and higher G allele frequency." (PMID 32998691, 2020). "Patients with coronary artery disease have lower circulating apelin concentrations, and these are lowest in those with symptomatic coronary artery disease." (PMID 37956047, 2023). "Our results are consistent with previous studies that found lower apelin levels in patients with stable coronary heart disease compared with controls." (PMID 34640437, 2021). "Recent reports showed that high glucose and MGO induced endoplasmic reticulum (ER) stress and myocyte apoptosis in ischemic heart disease was inhibited by apelin." (PMID 32517197, 2020). "In this meta-analysis, we summarized published results on circulating apelin concentration in association with coronary artery disease (CAD), apelin and APLNR genetic polymorphism(s) in predisposition to CAD risk and circulating apelin changes after surgical treatment for CAD." (PMID 28915675, 2017). "Apelin is a promising therapeutic target for ischemic heart disease." (PMID 36199867, 2022). "Meta-analysis of data indicated, that serum apelin (all forms) might be a prominent athero-protective marker against the development of coronary artery diseases." (PMID 29875677, 2018). "However, many studies have reported that the activity of apelin or Elabela may exert a beneficial effect on patients with coronary artery disease due to their vasodilatory effects on coronary arteries and their cardioprotective potential." (PMID 40299338, 2025). "Apelin serves as substrate for ACE2 and as a biomarker in cardiovascular diseases including coronary artery disease, stroke, ischemic heart disease, and infarction." (PMID 36145655, 2022). "The effect of apelin in angiogenesis in animal models of AMI and ischemic heart disease have been demonstrated with positive results." (PMID 29302260, 2017). "The effects of the apelinergic system components apelin (AP) and elabela (ELA) in the regulation of human cardiovascular homeostasis, and data concerning the relationship between ELA and AP and coronary artery disease (CAD) are yet unknown." (PMID 34640437, 2021). "Similarly apelin-36 levels were statistically not different in patients with or without ischemic heart disease (1.28 ± 0.29 ng/ml vs. 1.49 ± 0.38 ng/ml, p = 0.11)." (PMID 24433492, 2014).